IL6 (interleukin 6)
Diseases named in the same sentence as IL6 in open-access papers (continued):
Sharing a sentence is not in itself a finding about the gene and the disease.
tuberculosis (continued). "In Mtb stimulations, percentages and absolute counts of IL-6+ and TNF-α+ monocytes were similar in HIV-tuberculosis patients and controls." (PMID 28369200, 2017). "Since the proinflammatory cytokines, IL-1β, IL-6, and TNF-α, contribute to granulomatous inflammation in tuberculosis and other granulomatous diseases, we also examined their levels in granulomas from the two groups of mice." (PMID 25530957, 2014). "Increased mRNA expression of IFN-γ TNF-α, IL-6, IL-8 and IL-12 in tuberculosis granuloma and secretion of cytokines IL-1β, TNF-α and IL-6 in bronchoalveolar lavage fluid from involved sites of pulmonary TB have been reported." (PMID 23308269, 2013). "Fractalkine, IL-17, IL-6, IL-9, MIP-1β, CRP, VEGF, and IL-5 levels in saliva and IL-6, IL-2, SAP, and SAA levels in serum were significantly higher in tuberculosis patients (P < 0.05)." (PMID 24327799, 2013). "A reduction of IgE and IL-6 after TB treatment might also be explained by a reduction of a polyclonal stimulation or the use of anti-tuberculosis drugs, but to our knowledge a beneficial effect by anti-tuberculosis drugs on IgE levels has not been reported." (PMID 19558655, 2009). "Thus, key cytokines and chemokines such as IL-1β, IL-6, IL-8, TNF-α and IFN-γ play an important role in the pathogenesis of both COPD and tuberculosis." (PMID 40141021, 2025). "The combined use of BCG and M72 induced a potent anti-tuberculosis cytokine profile in cynomolgus monkeys, mainly IFN-γ, TNF-α, IL-2, and IL-6, which enabled the challenge animals to achieve long-term survival and reverse the outcome of tuberculosis progression." (PMID 37841250, 2023). "Similarly, the concentration of IL-6 was significantly increased and IL-4 decreased in SA, and the concentrations of INF-γ, IL-2, IL-4 and IL-10 were significantly lower in tuberculosis, compared to those in healthy subjects." (PMID 36982159, 2023). "Among the various cytokines, pro-inflammatory cytokines (TNF-α, IL-6, and IL-1β), and Th1 cytokines (IL-12, IFN-γ, and IL-2) are known to confer significant protection against tuberculosis, while anti-inflammatory cytokines (IL-10 and TGF-β) and type-I interferons (IFN-β) confer susceptibility." (PMID 35832818, 2022). "Therefore, we believe that an increased persistent level of IL-6 expression in the cohort of HIV/TB patients against the background of ART and reduced concentrations of IL-4 and IL-10 can serve as a possible marker of early detection of M. tuberculosis infection in HIV-infected individuals." (PMID 34835417, 2021). "Notably, based on principal component analysis, IL-6, IL-10, pSTAT3, and SOCS3 were the most influential factors that distinguished tuberculosis patients from healthy controls." (PMID 34035497, 2021). "They identified, IL-2, IL-6 and INF-γ among a few others as potential biomarker for tuberculosis." (PMID 33542363, 2021). "In a multivariate analysis, a relationship was found between the false positive rate and higher levels of interleukin-6, positive findings on an interferon-gamma release assay for tuberculosis, age < 50 years, and nondiabetic status." (PMID 32764429, 2020). "Chronic inflammation in tuberculosis patients—reflected by increased IL-6 plasma levels—did not account for dysfunctional T-cell responses and analysed T-cell exhaustion markers were only moderately correlated." (PMID 28582466, 2017). "HIV-tuberculosis patients had higher supernatant concentrations of CSF-3, IFN-ɣ, and IL-1-receptor-antagonist (IL-1RA) and lower concentrations of CSF-2, IL-12p40, IL-1β, IL-6, and TNF-α." (PMID 28369200, 2017).
tuberculosis (continued). "Mycobacteremic patients had lower absolute counts of IL-6+ monocytes compared with non-mycobacteremic tuberculosis patients in unstimulated samples and lower absolute counts of both IL-6+ and TNF-α+ monocytes in response to LPS." (PMID 28369200, 2017). "We, therefore, characterised and compared the expression of IL-6, TNF-α, IFN-γ, and IL-10 in whole blood of treatment naïve TB patients stimulated with heat-killed Mycobacterium tuberculosis stratified by HIV status and the level of CD4 count." (PMID 35025927, 2022). "IL-6 could discriminate tuberculosis patients with and without unfavorable treatment outcomes with an AUC of 0.69 (95%CI 0.55-0.85) for all participants and 0.66 (95%CI 0.42-0.85) when restricted to HIV coinfected participants (Figure-4)." (PMID 34711538, 2022). "Whereas systemic elevation of IL-6 is required for the induction of CRP in hepatocytes, LRG induction is mediated by multiple inflammatory cytokines and is observed not only in the liver but also in the inflamed tissues such as tuberculosis lesions of the lung." (PMID 32099022, 2020). "For example, mTB has been shown to induce IL-6 in vitro and in vivo and TNF-α plays a critical role in the protective immune response against tuberculosis (TB)." (PMID 30200570, 2018). "Due that plasma levels of IL-6, IFN-γ, IL-33, and CHIT1 appear to differentiate severe TB from mild APTB during the first 2 months of anti-tuberculosis treatment, we conducted an analysis using ROC curves to determine the diagnostic accuracy of these molecules, concerning APTB severity." (PMID 38137331, 2023). "Interestingly, this study discovered that the levels of TNF-a and IL-6 in sputum were not significantly different between active tuberculosis patients and controls, indicating that dysregulation of cytokines occurs mostly in the circulation, rather than the lungs." (PMID 35457250, 2022). "Moreover, the epidemiology of TB and the role of different cytokines (TNF-α, IL-6, IL-17, IL-12, and IL-23) in immune response against Mycobacterium tuberculosis (MTb) were reviewed." (PMID 28659665, 2017). "IL-6 is required in the rapid expression of an initial protective IFN-γ response during M. tuberculosis infection, while TNF-α is important in the control of mycobacterial infections, as illustrated by the reactivation of TB in the use of anti-TNF drugs." (PMID 22058091, 2012). "Our data showed that mycobacterium tuberculosis (Mtb)-specific IFN-γ, TNF-α, IL-2, IL-6, IL-10, IL-5, IP-10, IL-1Ra, CXCL-1 and MCP-1 responses based on QFT-Plus significantly differed between Mtb-infected (including ATB, LTBI and previous TB) and uninfected healthy populations." (PMID 38166667, 2024). "Although T cell-specific IL-6/IL-10 secretion has not been determined in TB-IRIS, triggers similar to those in acute tuberculosis patients may be assumed." (PMID 34035497, 2021). "We have found cytokines of predominantly myeloid origin (IL-6 and TNF-α) to be consistently elevated in patients with tuberculosis IRIS, compared with those who did not develop IRIS." (PMID 23097584, 2013). "Consistent with our previous finding in patients with tuberculosis, we found IL-6R expression on CD4+ T cells, but not plasma IL-6, correlated with the Th17 response in HBV infected individuals." (PMID 21639870, 2011). "Induction of IL-2, IL-6, IL-10 (not shown), IL-17A, IFN-g and was higher in participants with BCG scars, but only IL-6 were induced more in participants with no past history of tuberculosis." (PMID 29680481, 2018).
migraine (147 papers, 2011 to 2026). "Classically, TNFα and IL-6 have been associated in literature with migraine, as they are central mediators of both systemic and neurogenic inflammation." (PMID 41010614, 2025). "IL-6 is one of the key pro-inflammatory molecules in the central nervous system (CNS) and implicated in migraine disease in a recent meta-analysis." (PMID 38369488, 2024). "In a recent meta-analysis, IL-6, IL-8, IL-1β, and tumor necrosis factor α were the proinflammatory cytokines implicated in migraine patients." (PMID 38369488, 2024). "First, proinflammatory cytokines, such as interleukin (IL)-1b, IL-6, IL-8, and tumor necrosis factor-α, have been implicated in migraine pain and are increased during migraine attack, which play a critical role in the pathogenesis of IBD30." (PMID 38212517, 2024). "Neuroticism reflects an individual's emotional stability and is associated with IL-6 levels; IL-6-induced neuroinflammation is one of the pathophysiological mechanisms linked to migraines." (PMID 39822418, 2024). "Not only IL-1β but also TNF-α and IL-6, which are associated with migraine, as pointed out in this review, have already been established for clinical application in rheumatic diseases." (PMID 37176049, 2023). "Migraine is associated with high levels of IL-6 in some patients and high levels of IL-6 in humans results in neutrophil degranulation and subsequent release of neutrophil elastase." (PMID 37072694, 2023). "An association of inflammatory cytokines and migraine was revealed by a recent meta-analysis, that concluded higher levels of pro-inflammatory cytokines IL-6, IL-8 and TNF-α were detected in migraine patients compared to control subjects." (PMID 37940864, 2023). "In particular, we demonstrated the presence of the pro-inflammatory cytokines TNFα and IL-6, known to be associated with migraine pathology." (PMID 35614095, 2022). "Accordingly, in the present study, we reported that the decrease in CGRP plasma levels and gene expression was associated with a significant reduction of TNF-alpha and IL-6 gene expression in peripheral and central areas involved in migraine pain." (PMID 34685523, 2021). "We used the pro-inflammatory cytokine IL-6, which is upregulated during migraine attacks, but is a stimulus that is also implicated in pain states in other body regions." (PMID 34256692, 2021). "Histamine, leukotrienes, TNF-alpha, IL-6 and endothelin-1 released from MCs have been implicated in the pathophysiology of migraines." (PMID 33673856, 2021). "With regard to the pathophysiological mechanism of IL-6, a sensitization of the dural afferents has been suggested to contribute to migraine pathophysiology in association with IL-6 in the meninges." (PMID 33391152, 2020). "Along with IL-6, pro-inflammatory cytokine IL-18 is also up-regulated in serum of all migraine patients, albeit stronger in patients with the gene mutation." (PMID 28900389, 2017). "According to several studies, proinflammatory cytokines such as IL-1 (interleukin-1) and IL-6 have been implicated in migraine." (PMID 27191890, 2016). "An IgG-positive food elimination diet improved migraine and its comorbidities and reduced IL-6, TNF-α, and CGRP, which might be associated with the alleviated systemic chronic inflammation and downregulation of the sensitivity of trigeminal nerve endings." (PMID 41473187, 2025). "Furthermore, the expression of nitrogen oxides and their associated proinflammatory factors (e.g., IL-1, IL-6) is upregulated, not only in association with migraine onset but also in a way that leads to obsessive-compulsive-like behaviors." (PMID 39822418, 2024). "Several cytokines, including TNFα, IL-1, and IL-6, are implicated in the pathogenesis of migraine." (PMID 38903170, 2024).
migraine (continued). "Results obtained from animal models of headache also support that immunological responses associated with cytokines are involved in the mechanism of migraine, including enhanced production of several inflammatory cytokines, such as IL-1β, IL-6, and TNF-α during CSD." (PMID 37287623, 2023). "Elevated IL-6 levels were shown to be associated with headache chronification in migraine patients." (PMID 37940864, 2023). "Non-steroidal anti-inflammatory drugs (NSAIDs) have long been used in treating migraine attacks, so that multiple cytokines, such as IL-1β, tumor necrosis factor (TNF), and IL-6, have been associated with the pathogenesis of migraine, as their levels are altered in migraine patients." (PMID 36247795, 2022). "One particular inflammatory mediator that has been implicated in migraine is interleukin-6 (IL-6)." (PMID 34256692, 2021). "Additionally, decreased levels of cortisol and elevated levels of pro-inflammatory cytokines (e.g. tumor necrosis factor-alpha, interleukin-6) in patients with PTSD have been suggested to be linked to migraine." (PMID 28685258, 2017). "In addition, we examined several other molecules putatively involved in migraine pathophysiology: SP, IL-1β, IL-6 and TNF-α which have all been shown to be associated with activation of the trigeminovascular system." (PMID 28337634, 2017). "Inhibition of PD-1 amplified migraine-induced hyperalgesia was accompanied by increased calcitonin gene-related peptide, interleukin-1β, tumor necrosis factor α, interleukin-6, and interleukin-18 in the trigeminal ganglia of mice." (PMID 40002809, 2025). "Our preliminary findings suggest a potential role for peripheral inflammatory markers, including specific microRNAs (miR-197, miR-101, and miR-143) and cytokines (TNF-α, IL-6, and IL-17A), in the pathophysiology of migraine." (PMID 41010614, 2025). "Mechanistically, Mt2 regulates cerebrovascular compliance via modulating the release of migraine‐associated mediators (CGRP, IL‐6, TNF‐α), thereby establishing an interface between vascular tone dysregulation and migraine‐like pain thresholds." (PMID 41194575, 2025). "In summary, we provide clinical evidence that the IgG-positive food elimination diet was beneficial to migraine and its comorbidities and reduced the production of IL-6, TNF-α, and CGRP." (PMID 41473187, 2025). "The difference in the change of “days with migraine in past 4 weeks” between the sham and true diet groups was significantly attenuated after adjusting for IL-6 and TNF-α." (PMID 41473187, 2025). "Pro-inflammatory cytokines such as IL-1β, IL-6, IL-8, and TNF-α are implicated in both migraines and GIDs, contributing to visceral pain and systemic inflammation." (PMID 39861467, 2025). "A study has shown that calcitonin gene-related peptide (CGRP), a key neuropeptide in migraine pathophysiology highly correlates (r = 0.94) with IL-6 levels in patients with migraine." (PMID 40236898, 2025). "The water extract significantly reduced the levels of inflammatory factors such as NO and IL-6 in the serum of migraine rats; ethanol extract inhibited TNF-α secretion of macrophages." (PMID 41020864, 2025). "TNF-α and IL-6 are classic pro-inflammatory cytokines that have been widely investigated in many migraine studies." (PMID 41473187, 2025). "IL-6 is widely recognized in migraine literature – elevated during attacks and interictally in many studies, and one of the few cytokines consistently higher in CM populations." (PMID 41377228, 2025). "Preclinical research also shows that cytokines such as IL-1β and IL-6 can activate and sensitize meningeal and muscle nociceptors, suggesting their role in contributing to migraine pain." (PMID 40149800, 2025). "Elevated levels of inflammatory cytokines, such as IL-6, TNF-α, and CGRP, are implicated in pain transmission and vascular changes during migraine episodes." (PMID 40426647, 2025).
migraine (continued). "In animal models, nitroglycerin-induced migraine correlates with elevated IL-1β and IL-6 levels, indicating delayed meningeal inflammation." (PMID 40426647, 2025). "This analysis revealed significant downregulation of NOS2 (inducible nitric oxide synthase) along with key migraine‐associated inflammatory factors, including TNF‐α, IL‐6 and CGRP." (PMID 41194575, 2025). "But the levels of IL-6, IL-5, and IL-8 in the migraine group were lower than those in the control group." (PMID 38356891, 2024). "In a recent study, the correlation between higher serum IL-6 levels and migraine chronification has been reported." (PMID 38369488, 2024). "Interleukin 6 (IL-6) is a proinflammatory and nociceptive cytokine in the trigeminal system and was shown to be elevated in patients with migraine." (PMID 38369488, 2024). "We also found associations between the expression of CALCA, EDN1, IL6, NOS3, VCAM1, and VEGF and measures of cerebrovascular function and migraine-related disability when menstrual phase (i.e., follicular, mid-cycle, or luteal) was accounted for." (PMID 38338971, 2024). "This tendency of hypersensitivity was similar to hypersensitivity observed previously in an IL-6-induced migraine model." (PMID 38802819, 2024). "Another inflammatory mediator implied in migraine is IL-6, a proinflammatory cytokine that is shown to be increased in the internal jugular blood of migraine patients during a migraine attack." (PMID 38812640, 2024). "Numerous studies indicate an elevation in pro-inflammatory cytokines, including IL-1β, IL-6, IL-8, and TN-αduring the interictal phase of migraines." (PMID 39015315, 2024). "Serum CGRP levels were correlated with serum IL-6 levels similar to a previous study in which CGRP levels were correlated with IL-6 levels during migraine attacks." (PMID 38369488, 2024). "Some studies reported higher IL-6 levels in migraine while others showed similar IL-6 levels in both migraine patients and healthy controls." (PMID 38369488, 2024). "Previous studies have suggested that inflammatory reactions play a certain role in the occurrence and development of adult migraine or animal models, which are most on the pro-infammatory, such as cytokines IL-1β, IL-6, TNF-α, and CGRP unfolded." (PMID 38356891, 2024). "With regard to the pathophysiological mechanism of IL-6 and migraine, IL-6 is considered to be one of the triggers of the trigeminovascular system." (PMID 39274228, 2024). "On the other hand, during migraine attacks, there is an increase in the release of pro-inflammatory cytokines such as IL-1β, IL-6, and TNF-α." (PMID 39107712, 2024). "A case-control study investigating newly diagnosed migraine patients revealed significantly higher serum IL-1beta and IL-6 concentrations, while the IL-10 serum levels were lower compared to those of healthy controls." (PMID 36835524, 2023). "The activation of microglia and subsequent release of various pro-inflammatory cytokines such as IL-6 and IL-1β lead to hyperalgesia or allodynia in experimental migraine models." (PMID 37090989, 2023). "Peripheral levels of pro-inflammatory cytokines, such as interleukin-1β (IL-1β), IL-6, IL-8, and tumor necrosis factor-α (TNFα) were elevated in patients with migraine." (PMID 37287623, 2023). "In patients with migraine CGRP levels have been shown to highly correlate (r = 0.94) with IL-6 levels." (PMID 37016284, 2023). "A clinical study investigating M0 and MA patients in both attack and pain-free periods revealed that serum levels of IL-6 were significantly higher in migraine patients during attacks compared to those in controls." (PMID 36835524, 2023). "They did find a trend for the pro-inflammatory cytokines TNF-α and IL-6 to be higher, and the anti-inflammatory cytokine IL-10 to be decreased, in the interictal period in migraine compared to healthy controls." (PMID 37016284, 2023).